NPPB (natriuretic peptide B)
Description:
[Brain natriuretic peptide 32]: Cardiac hormone that plays a key role in mediating cardio-renal homeostasis. May also function as a paracrine antifibrotic factor in the heart (By similarity). Acts by specifically binding and stimulating NPR1 to produce cGMP, which in turn activates effector proteins that drive various biological responses. Involved in regulating the extracellular fluid volume and maintaining the fluid-electrolyte balance through natriuresis, diuresis, vasorelaxation, and inhibition of renin and aldosterone secretion. Binds the clearance receptor NPR3. [NT-proBNP]: May affect cardio-renal homeostasis. Able to promote the production of cGMP although its potency is very low compared to brain natriuretic peptide 32. [BNP(3-32)]: May have a role in cardio-renal homeostasis. Able to promote the production of cGMP.
Synonyms: BNP; Iso-ANP
Tractability: Antibody: UniProt places it where antibodies can reach, with high confidence; its Gene Ontology location is reachable by antibodies, with high confidence; UniProt predicts a signal peptide or a membrane-spanning region.
Gene: Protein-coding gene on chromosome 1 (11,857,464 to 11,858,976, reverse strand). Ensembl gene ENSG00000120937.
Subcellular location: Secreted (NT-proBNP); Secreted (proBNP(3-108)); Secreted (Brain natriuretic peptide 32); Secreted (BNP(3-32))
Subcellular location (Human Protein Atlas): Vesicles; Cytosol; Predicted to be secreted
Gene Ontology:
Molecular function: hormone receptor binding; protein binding; signaling receptor binding; diuretic hormone activity; hormone activity
Biological process: cGMP biosynthetic process; protein folding; receptor guanylyl cyclase signaling pathway; blood vessel diameter maintenance; body fluid secretion; cardiac conduction system development; cell surface receptor signaling pathway; negative regulation of angiogenesis; negative regulation of cell growth; negative regulation of systemic arterial blood pressure; neuropeptide signaling pathway; positive regulation of renal sodium excretion; positive regulation of urine volume; regulation of blood pressure; regulation of vascular permeability; system process
Cellular component: extracellular region; protein-containing complex; cytoplasm
Genetic constraint (gnomAD): Loss-of-function variants: 13 observed, 12.52 expected, observed/expected ratio (o/e) 1.04, 90% interval 0.67 to 1.63. The upper end of that interval is the gene's LOEUF score, 1.63, which puts it in group 6 of 6, group 1 being the genes least tolerant of losing a copy. Missense variants: 184 observed, 181.1 expected, observed/expected ratio (o/e) 1.02, 90% interval 0.9 to 1.15. Synonymous variants: 66 observed, 79.11 expected, observed/expected ratio (o/e) 0.83, 90% interval 0.68 to 1.02.
Homologues: Orthologues: chimpanzee NPPB (98% identical), macaque NPPB (89% identical), pig NPPB (51% identical), rat Nppb (33% identical), tropical clawed frog nppb (32% identical), mouse Nppb (31% identical), zebrafish nppb (22% identical). Paralogues in human: NPPA (27% identical).
Diseases named in the same sentence as NPPB in open-access papers:
NPPB is named in the same sentence as 697 diseases in open-access papers, as found by Europe PMC text mining. Sharing a sentence is not in itself a finding about the gene and the disease. The quoted sentences say what the papers report.
heart failure (3,389 papers, 2004 to 2026). Inability of the heart to pump blood at an adequate rate to meet tissue metabolic requirements. "Consistent with myocardial dysfunction, expression of genes linked to cardiac failure such as Nppa (natriuretic peptide A) and Nppb (natriuretic peptide B) were markedly upregulated in the TAZG197V mice heart samples." (PMID 37533404, 2023). "The RCAN1-4 transcript levels in AS correlated with those of heart-failure signature-molecule brain natriuretic peptide (BNP, encoded by NPPB), indicating that NFAT activation was related to severity of LV stress." (PMID 39086965, 2022). "The most notable associations included NT-proBNP for atrial fibrillation (P = 6.31 × 10-313), followed by NPPB (P = 1.03 × 10-164) and GDF15 for heart failure (P = 1.21 × 10-166)." (PMID 40927895, 2026). "Their results suggest that ADAMTS2 plays a key role in modulating the expression of other heart failure-related genes (including natriuretic peptide A (Nppa) and natriuretic peptide B (Nppb)) in response to isoproterenol treatment." (PMID 40837410, 2025). "Compared with the ISO group, the heart failure marker genes NPPa and NPPb; fibrosis-related gene Postn and hypertrophy-related gene Myh7 also showed clear upregulation in the ISO/PE group." (PMID 40129768, 2025). "Among the most notable associations with NCDs include a strong link between natriuretic peptide B (BNP) and heart failure and inflammatory bowel disease (IBD) associated with higher plasma levels of prostaglandin-H2 D-isomerase." (PMID 39891174, 2025). "Natriuretic peptides, particularly NPPA (translated to ANP) and NPPB (translated to BNP), have emerged as valuable predictors of stroke and heart failure, including NT-proBNP." (PMID 40296161, 2025). "The gene NPPB encodes for BNP (brain natriuretic peptide), a well-known clinical biomarker for heart failure, and is upregulated during hypertrophy due to a return to a fetal-like gene expression program." (PMID 37344639, 2023). "We stratified the data set by expression of Natriuretic peptide B (NPPB), a clinical marker of heart failure and perivascular fibrosis, and defined hypertrophic hearts as the top 30% of NPPB expression and healthy hearts as the bottom 30% of NPPB expression." (PMID 36976650, 2023). "Laboratory studies revealed an increase in cardiac enzymes (high sensitivity troponin I-hsTnI level was at 0.1174 ng/mL) along with heart failure indicators (increased brain natriuretic peptide-BNP up to 432 pg/mL)." (PMID 36547424, 2022). "The three genes with random absolute values of LogFC and indicators of heart failure (natriuretic peptide B, NPPB) were detected: carboxylesterase 1D (CES1D), whirlin (WHRN), and WNK lysine deficient protein kinase 2 (WNK2)." (PMID 35886059, 2022). "Carboxylesterase 1D (CES1D), whirlin (WHRN), and WNK lysine deficient protein kinase 2 (WNK2) were the three genes with random absolute values of LogFC and indicators of heart failure (natriuretic peptide B, NPPB) detected." (PMID 35886059, 2022). "The results of the microarray showed the expression of NPPB, which codes for brain natriuretic peptide (BNP), a well-known protein associated to decompensated heart failure, was around 15-fold higher in worsening-LVF compared with preserved-LVF." (PMID 32708358, 2020). "Natriuretic peptide A (NPPA, ANP) and B (NPPB, BNP) have emerged as important candidates for the development of therapeutic agents for heart failure." (PMID 27324127, 2016). "The other two blood tests are used to diagnose heart failure (natriuretic peptide B, also known as BNP) and to monitor tumor progression (carcinoembryonic antigen, also known as CEA)." (PMID 27439507, 2016). "Re-expression of NPPB/BNP and its secretion into plasma has become an important clinical biomarker for diagnosis and treatment of heart failure and LVH." (PMID 25255322, 2014).
heart failure (continued). "NPPB encodes brain natriuretic peptide (BNP) and is a well-established serum marker used in the prognosis of heart failure in the clinic." (PMID 25051449, 2014). "The normalization strategy was tested by comparing RT-qPCR data of both normalized and raw expression levels of brain natriuretic peptide precursor (NPPB), a gene known to be up-regulated in heart failure." (PMID 19114010, 2008). "Additionally, the expression level of heart failure markers was detected in hearts, including natriuretic peptide A (Anp), natriuretic peptide B (Bnp) and beta-myosin heavy chain (β-Mhc)." (PMID 35310994, 2022). "As a means of better understanding the underlying molecular mechanisms of heart failure, much effort has been made to elucidate the mechanisms regulating expression of fetal cardiac genes, including NPPA and NPPB, the genes respectively encoding ANP and BNP." (PMID 36009824, 2022). "Proteomic studies have made it possible to include in guidelines natriuretic peptide B-type (BNP) and/or N-terminal prohormone natriuretic peptide B-type (NT-proBNP) for the diagnosis of heart failure and prognostic evaluation of patients with chronic heart failure." (PMID 34948066, 2021). "In addition, the intensities in endothelial cells correlated positively with log‐transformed brain natriuretic peptide BNP (Log10BNP) and negatively with levels of hemoglobin and hematocrit, suggesting the influence of heart failure." (PMID 30885039, 2019). "Importantly, adenoviral overexpression of glypican-6 in cultured cardiomyocytes increased protein synthesis and induced mRNA levels of the pro-hypertrophic signature gene ACTA1 and the hypertrophy and heart failure signature genes encoding natriuretic peptides, NPPA and NPPB." (PMID 27768722, 2016). "BMP10 induced upregulation of TGFβ pathway transcripts, increased expression of genes related to AF and heart failure, including PITX2 and NPPB, and increased relative contraction times in ventricular EHTs." (PMID 41090224, 2025). "Next, we assessed the expression of natriuretic peptide B (NPPB), a well-established biomarker of heart failure." (PMID 40184463, 2025). "Upregulated genes in Vehicle include NPPB, COL1A1, FMOD, LOX and MMP9, among others, some of which are related with pro-fibrotic processes and heart failure." (PMID 37342444, 2023). "Heart failure is characterized by increased wall tension that leads to increased synthesis of the natriuretic peptide BNP and its N-terminal fragment of proBNP (NT-proBNP)." (PMID 35381849, 2022). "In heart failure, NPPB is expressed at a high level in DCM, and patients with higher BNP level have a worse cardiac function." (PMID 34970603, 2021). "To further explore the effect of WPS on the cardiac functions at the molecular level, we investigated the expression of cardiac failure markers ANP/NPPA and BNP/NPPB in all experimental groups at 72 h post-fertilization." (PMID 34770174, 2021). "For the prediction of a heart failure before it happens, some cardiac markers can be measured includingANP/NPPA and BNP/NPPB." (PMID 34770174, 2021). "Indeed, CLCN6 might not be mechanistically implicated in heart failure at all but instead it might modify expression of NPPB (the gene encoding BNP) in trans, or might directly regulate NPPB in cis given the strong linkage disequilibrium (LD) at the locus." (PMID 28228157, 2017). "Notably, CM1 is enriched with genes classically increased in adult heart failure such as ANKRD1 and NPPB, which highlights an important difference in myocyte cell state diversification between heart failure and single ventricle hearts." (PMID 40502733, 2025). "Hypomethylation of the promoters of NPPA, NPPB, ACTN2, NEBL, and MYO18B may serve as biomarkers for the early detection of heart failure (HF)." (PMID 40296161, 2025). "In addition, natriuretic peptide B (NPPB), which serves as a prognostic indicator of heart failure, was significantly increased in transcriptional level." (PMID 40568929, 2025).
heart failure (continued). "It included proteins like NT-proBNP (NPPB), growth differentiation factor 15 (GDF15), and fibroblast growth factor 23 (FGF23), markers that are known to be tightly related to heart failure and further systemic diseases, but also inflammatory proteins (CXCL8, CSF1)." (PMID 38999939, 2024). "In addition, in our analysis results, NPPA, NPPB, COL1A2, ASPN, ANKRD1 and CTGF were all confirmed to be closely related to heart failure in dilated cardiomyopathy in various studies." (PMID 34970603, 2021). "This study is aimed at investigating natriuretic peptide B (NPPB) coexpression genes and their pathways involved in heart failure (HF) among patients both with and without type 2 diabetes mellitus (T2DM)." (PMID 32802835, 2020). "First, we assessed whether these 28 WNT-related genes and two well-described heart failure genes—NPPA and NPPB—exhibited differential expression between NF/pRV/RVF separately for both DCM and ICM using Kruskal–Wallis to compare log2fold changes." (PMID 33134326, 2020).
diabetes (991 papers, 2008 to 2026). "Given that BNP and atrial natriuretic peptide bind to the same receptor and have the same biological activity, the elevated levels of BNP cause an increase in the glomerular hydraulic pressure and ultimately induce albumin excretion in patients with diabetes mellitus." (PMID 26473035, 2015).
Hypertension (851 papers, 2005 to 2026). The presence of chronic increased pressure in the systemic arterial system. "A genome-wide association study of circulating NPPB identified a variants in the NPPB locus, and these variants were also associated with lower systolic and diastolic blood pressure as well as lower risk of hypertension." (PMID 33210602, 2020). "The rs198389 G allele in the NPPB promoter is associated with elevated levels of NT‐proBNP throughout adult life, reduced blood pressure, hypertension and cardiovascular mortality, and increased lifespan." (PMID 28341776, 2017). "We hypothesized that the rs198389 variant, which has been associated with increased NPPB transcription, may be associated with NT‐proBNP levels across age and different stimuli as well as with hypertension and mortality." (PMID 28341776, 2017). "Several studies have demonstrated a link of ANP (NPPA), BNP (NPPB), and NPRA (NPR1) polymorphisms with hypertension and CVDs in humans." (PMID 34489721, 2021). "It has been reported that a positive association exists between the polymorphisms of NPPA, NPPB, and NPR1 causing essential hypertension and LHV." (PMID 34489721, 2021). "In this study, we find that genetically elevated brain type natriuretic peptide (NPPB) was protective against hypertension." (PMID 33210602, 2020). "cGMP is formed in response to NO and natriuretic peptides, including the atrial natriuretic factor ANF (NPPA) (BN) and the brain natriuretic factor ANFB (NPPB) (BN), and has been shown to modulate hypertension via different mechanisms, as vasorelaxation or renin reduction." (PMID 38326862, 2024). "Like the ANP knockout mouse model, deletion of the BNP gene (NPPB) in rats resulted in hypertension and end organ damage, while BNP gene delivery chronically increased BNP in spontaneously hypertensive rats, reduced blood pressure and prevented organ dysfunction." (PMID 35222065, 2021). "Natriuretic peptide B (NPPB), QPCT, and inhibitor of growth 4 (ING4) were also recognized as having a significant mediating effect on glucosamine intake for hypertension protection." (PMID 39596173, 2024).
atrial fibrillation (638 papers, 2008 to 2026). A disorder characterized by an electrocardiographic finding of a supraventricular arrhythmia characterized by the replacement of consistent P waves by rapid oscillations or fibrillatory waves that vary in size, shape and timing and are accompanied by an irregular ventricular response. "For the observed associations for NPPB, ITIH3, and IGFBP7 with multiple outcomes and for the association of SVEP1 with atrial fibrillation, our findings were negative for colocalization, suggesting two different causal variants for protein level and outcome." (PMID 38225249, 2024).
cardiac hypertrophy (521 papers, 2007 to 2026). "Three pro‐hypertrophy markers, namely natriuretic peptide A, natriuretic peptide B and myosin heavy chain beta, are commonly used to evaluate myocardial hypertrophy." (PMID 37985436, 2024). "For example, the hypomethylation of NFATc2 is predicted to activate RCAN1 and NPPB, which are related to exercise-induced cardiac hypertrophy and concentric hypertrophic cardiomyopathy, respectively." (PMID 38793603, 2024). "ChIP-seq further unveiled EBF1 occupancy on promoters of genes linked to cardiac hypertrophy, including MEF2C and NPPA/NPPB." (PMID 39239522, 2024). "In particular, MYRIP was associated with cardiac hypertrophy signaling (e.g., NFAT pathway, NPPA, and NPPB) and aldosterone signaling." (PMID 33679876, 2021). "Atrial natriuretic peptide (NPPA) and Brain natriuretic peptide (NPPB) are hormones synthesized in the heart that act to inhibit maladaptive cardiac hypertrophy." (PMID 30890961, 2019). "In addition, we observed that genes associated with cardiac hypertrophy, such as NPPA, NPPB, TNNC1, and DES, were markedly upregulated in the mutant compared with WT iPSC-CMs." (PMID 40779454, 2025). "Interestingly, we observed that LPA treatment (1 mg/kg per day) promoted cardiac hypertrophy, as indicated by hematoxylin and eosin staining of cardiac tissues, measurement of myocyte size, and natriuretic peptide B (BNP) expression." (PMID 30283359, 2018). "This potential cardiac hypertrophy induced by pregnancy in descendants of fructose-fed mothers and by fructose consumption during their own pregnancy coincided with an increase in the gene expression of Natriuretic peptide B (NPPB), a typical marker of cardiac hypertrophic." (PMID 39335874, 2024). "We examined cardiac hypertrophy-related genes and found that the mRNA levels of BNP (Natriuretic Peptide B), Myh7 (Myosin Heavy Chain 7), and Gata4 (GATA Binding Protein 4) were significantly up-regulated in maternal DHT-treated group." (PMID 37642904, 2024). "Cardiac fetal genes (NPPA, NPPB, MYH6, MYH7 and ACTA1) are usually only expressed during fetal life and re-expression of these genes in adult life is an indicator of pathologic cardiac hypertrophy." (PMID 25051449, 2014). "In addition to HOPX, we also observed an abrupt elevation in the expression of natriuretic peptide B (NPPB), a gene related to cardiac hypertrophy in adult heart, at an early stage of CM differentiation (T09), which dropped quickly thereafter." (PMID 31722692, 2019). "Furthermore, through Pearson correlation analysis in R, we discovered a significant positive correlation between SSC5D and the cardiac hypertrophy marker genes A-type natriuretic peptide (NPPA) (R = 0.6, p = 3.1e-11) and B-type natriuretic peptide (NPPB) (R = 0.46, p = 1.3e-6)." (PMID 37123263, 2023).
chronic heart failure (512 papers, 2005 to 2026). "This is in contrast to a study of chronic heart failure without valvular disease, where men with low levels of the natriuretic peptide BNP were found to have a low risk of CSA." (PMID 26214183, 2015).
myocardial infarction (452 papers, 2005 to 2026). Gross necrosis of the myocardium, as a result of interruption of the blood supply to the area, as in coronary thrombosis. "Conversely, human-Geneformer model predicted that deleting ANKRD1 and NPPB from myocardial infarction cells would revert them to a more normal cellular state." (PMID 40106407, 2025). "To illustrate such approach, we present recent results showing that the exogenous administration of the natriuretic peptide BNP triggers “endogenous” cardiac regeneration, following experimental myocardial infarction." (PMID 26880973, 2016). "The original human-Geneformer predicted that activation of NPPB and ANKRD1, as well as deletion of MYH7, could drive normal heart cells towards myocardial infarction state." (PMID 40106407, 2025).
coronary artery disease (440 papers, 2007 to 2026). "Several single nucleotide polymorphisms (SNPs) in the NPPB gene region have been associated with NT-proBNP levels and CVD outcomes in population studies and clinical studies of patients with coronary artery disease." (PMID 33720941, 2021).
Stroke (389 papers, 2008 to 2026). Sudden impairment of blood flow to a part of the brain due to occlusion or rupture of an artery to the brain. "Additionally, the AGTRAP‐PLOD1 locus gene cluster where CLCN6 is localized has been associated with stroke along with other BP regulatory genes such as MTHFR, NPPA, and NPPB." (PMID 35927940, 2022).